ADH1B (alcohol dehydrogenase 1B (class I), beta polypeptide)
Diseases named in the same sentence as ADH1B in open-access papers (continued):
Sharing a sentence is not in itself a finding about the gene and the disease.
esophageal cancer (continued). "According to an association study of ADH1B and ALDH2 polymorphisms, East Asian populations may be more susceptible to the carcinogenic effect of alcohol, including esophageal cancer and head and neck cancer." (PMID 35670037, 2023). "Genetic polymorphisms of ADH1B, ADH1C and ALDH2 have been reported involving in the development and progression of many cancers, such as gastric cancer, head and neck cancers, esophageal cancer, and pancreatic cancer." (PMID 35280985, 2022). "In studies involving East Asian populations, the presence of genetic polymorphisms in ADH1B (rs1229984) and ALDH2 (rs671), as well as alcohol consumption, individually or in combination, increase the risk of breast cancer, HNC, and esophageal cancer." (PMID 34680942, 2021). "Considering that drinking is a major risk factor of esophageal cancer, regional distributions of DAF spectra of the ADH1B and ALDH2 functional alleles partly explain its similarity with those of drinking habit, and as a consequence, prevalence of esophageal cancer." (PMID 29691385, 2018). "Several studies have identified the relationship between ADH1B polymorphism and esophageal cancer susceptibility, but the consistent results were not obtained." (PMID 27450204, 2016). "Collectedly, these results indicate that ADH1B may play a role in the proliferation of esophageal cancer cell line." (PMID 24485404, 2014). "Our results suggested a potential role of ADH1B SNPs on the etiology of esophageal cancer." (PMID 24485404, 2014). "This study focuses on analyzing associations between SNPs of essential enzymes for alcohol metabolism ADH1B, ADH1C, and ALDH2 and survival in esophageal cancer patients receiving postoperative radiotherapy." (PMID 36212135, 2022). "With respect to downregulated genes, C16orf89, AR, CKB, ADH1B, and NCAM1 were the leading downregulated genes in patients with esophageal cancer." (PMID 33828156, 2021). "Our analysis showed that following five genes were most significantly downregulated in esophageal cancer: C16orf89 (9.78E−08), AR (1.01E−07), CKB (1.17E−07), ADH1B (1.79E−07), and NCAM1 (2.15E−07)." (PMID 33828156, 2021). "Our data showed that participants carrying ADH1B rs1229984 TC/CC and ALDH2 rs671 GA/GG were at higher risk of esophagus cancer than noncarriers." (PMID 35670037, 2023).
alcohol use disorder (17 papers, 2007 to 2025). "The ALDH2*1 allele was found as a risk factor for alcohol abuse and alcohol cirrhosis, and combined genotypes of ADH1B rs1229984, ADH1C rs698 and ALDH2 rs671 with non‐acetaldehyde accumulation increase alcohol cirrhosis risk." (PMID 40730494, 2025). "This genetic association study evaluates the estimability and generalizability of a polygenic score, compared with family history and ADH1B, in assessing the risk of alcohol use disorder among populations of European ancestry." (PMID 39786404, 2024). "The ADH1B rs1229984 T allele causes a rapid conversion of ethanol to acetaldehyde and leads to an aversive reaction to alcohol and a protective effect against alcohol use disorder." (PMID 35670037, 2023). "The first of the studied polymorphisms of the ADH1B gene (rs1229984) has been evaluated in the context of the pathogenesis of alcohol use disorder (AUD)." (PMID 37510297, 2023). "Individuals with the ADH1B rs1229984 (TC) or rs1229984 (TT) genotypes are more likely to experience drinking discomfort, reducing the risk of alcohol use disorder." (PMID 35670037, 2023). "The ADH1B*2 allele has been shown to decrease the occurrence of alcohol abuse and alcohol addiction in Asians and in the Caucasian and Jewish populations." (PMID 33924016, 2021). "rs1229984 is a non-synonymous SNP in the alcohol dehydrogenase 1B gene (ADH1B); the minor allele (A) carriers have a version of ADH1B that oxidises alcohol more rapidly, and as such A carriers are at a reduced risk for alcohol use disorder." (PMID 31767999, 2021). "ALDH2 and ADH1B polymorphisms are associated with a higher risk for bladder cancer and alcohol abuse." (PMID 28536537, 2017). "Alcohol abuse also mediates the ADH1B effect on hepatitis B-related hepatocellular carcinoma risk, and head and neck squamous cell carcinoma." (PMID 28536537, 2017). "The high prevalence of the ALDH2*2 and ADH1B*2 alleles in a large percentage of Asian subgroups has been studied as a potential protective factors against alcohol abuse, yet some individuals who possess these genes still engage in problematic alcohol use." (PMID 27159808, 2016). "Concerning the four SNPs of interest and the disease-related factors, cognitive impairment (SNPs of APOE, ADH1B, MTHFR), alcohol abuse (ADH1B variant), caffeine consumption (SNPs of CYP2A1, MTHFR), and homocysteine levels (MTHFR variant) appeared as the mostly represented traits." (PMID 36011409, 2022). "ADH1B rs1229984 is a well-known coding SNP in the 4q23 region associated with alcohol abuse." (PMID 31591379, 2019). "The researchers concluded that the presence of the ADH1B*3 allele may be associated with a less rewarding subjective response to alcohol, an effect that has been associated with protection from the development of alcohol use disorders in other populations." (PMID 17718396, 2007). "Genes such as ADH1B and ALDH2 have been shown to be protective in Asian populations, while ADH1C has been shown to increase the risk for alcohol use disorder." (PMID 38359015, 2024). "Although the ADH1B*2 and ALDH2*2 alleles both can serve as protective factors against alcohol abuse, they do not seem to eliminate alcohol consumption altogether." (PMID 27159808, 2016).
breast carcinoma (16 papers, 2005 to 2025). "A study on post-menopausal women from the Prostate, Lung, Colorectal and Ovarian (PLCO) Cancer Screening Trial found significant interactions between rs1229984-GG in ADH1B and all levels of alcohol intake and risk of breast cancer." (PMID 37308906, 2023). "Alcohol dehydrogenase 1B (ADH1B) polymorphisms have been reported to be associated with bladder cancer, gastric cancer, and breast cancer risk." (PMID 34903206, 2021). "For example, they found that alcohol consumption was positively associated with breast cancer risk among women with the GG allele of alcohol dehydrogenase 1B (ADH1B) gene, but appeared to be inversely associated with risk among women with the GA or AA allele." (PMID 31409314, 2019). "In all, 65 breast cancer patients (10.6%) and 109 controls (10.1%) were heterozygous or homozygous carriers of the ADH1B*2 allele, corresponding to allele frequencies of 0.06 and 0.05, respectively." (PMID 15886702, 2005). "We employed a population-based case–control study of women up to age 50 years to examine the potential effect of ADH1B genotype on the association between alcohol consumption and breast cancer risk." (PMID 15886702, 2005). "In contrast, among women with ADH1B*1/*1 genotype, breast cancer risk increased with increasing alcohol consumption (P=0.03)." (PMID 15886702, 2005). "However, the association between alcohol consumption and breast cancer was more prominent in those with ADH1B His/His or those that were homozygous for the major allele in both ADH1B and ALDH2." (PMID 32300124, 2020). "In the present study, the association between alcohol consumption and breast cancer risk stratified by ALDH2 and ADH1B polymorphism status, despite the presence of variants and alcohol intake, specifically a high dose of alcohol intake, increased the risk of breast cancer." (PMID 32300124, 2020). "Our data raise the possibility of an effect modification of the association between alcohol consumption and breast cancer risk by ADH1B genotype in our study population, which was apparent only at the highest consumption category of 12 g or more alcohol per day." (PMID 15886702, 2005). "The reduction in breast cancer risk associated with high consumption levels in carriers of the ADH1B*2 allele in our study could therefore be explained by a higher alcohol elimination rate in these subjects." (PMID 15886702, 2005). "Earlier genetic studies found that rs1229984 in ADH1B and rs698 in ADH1C modify the alcohol association with breast cancer, particularly in pre-menopausal women." (PMID 37308906, 2023). "Another example is ADH1B, one of the most downregulated genes in breast cancer samples in TCGA, which showed significantly higher TSS coverage after AECT imputation (p = 3.23 × 10−6, Wilcoxon rank-sum test)." (PMID 34926480, 2021). "The associations between genetic polymorphisms in ADH1B (rs1229984) and ALDH2 (rs671), alcohol consumption, the effect of a combination of the two polymorphisms, and breast cancer risk were studied in a population of East-Asian women." (PMID 32300124, 2020). "Finally, because we lack genotype data, we are unable to determine whether the observed inverse association between alcohol consumption (particularly wine consumption) and risk of breast cancer-specific mortality is modified by genotypic variation (e.g., ADH1B)." (PMID 31409314, 2019). "We performed combinatorial ranking on the TCGA Breast Cancer dataset with 10 genes of Gcore (ADH1B was excluded due to missing data in this cohort)." (PMID 28361034, 2017). "Although ethanol metabolism mainly occurs in the liver and is mediated by hepatic alcohol dehydrogenase IB (ADH1B), breast cancer cells are shown to express moderate levels of cytochrome P450 2E1, another enzyme to oxidize ethanol." (PMID 26655092, 2016).
breast carcinoma (continued). "We conducted a case–control study to determine the impact of the interaction of the effects of alcohol consumption and polymorphisms in the alcohol-metabolizing enzymes ADH1B and ALDH2 on the risk of female breast cancer in Japan." (PMID 19667493, 2009). "Among all 9 genotype combinations, only the combination of ADH1B*1/*2 and ALDH2*2/*2 was significantly associated with a reduced risk of breast cancer, although it should be mentioned that all subjects with this genotype combination were never-drinkers." (PMID 19667493, 2009). "In a study of 623 female breast cancer patients and 1845 control subjects from East Asia, it was found that alcohol consumption increased the risk of breast cancer regardless of ADH1B and ALDH2 genotypes." (PMID 36310188, 2023). "The ADH1B rs1229984 polymorphism, and combined effects of the rs671 and rs1229984 polymorphisms, did not reveal any significant association with breast cancer." (PMID 32300124, 2020). "Considering the subgroup of women with possibly higher alcohol susceptibility, the effects of the ADH1B and ALDH2 genes on alcohol drinking behavior and breast cancer risk might require further investigation." (PMID 32300124, 2020). "One study reported a marginally protective association for ADH1B IVS1 + 896 A > G with breast cancer risk; however, the same SNP considered in this study did not exhibit any association." (PMID 32300124, 2020). "Alcohol consumption increased breast cancer risk, but for cases homozygous for the major alleles of ADH1B or/and ALDH2 polymorphisms, the increment was more prominent, suggesting that this was a high-risk population for breast cancers associated with alcohol consumption." (PMID 32300124, 2020). "In terms of breast cancer, ADH1B itself did not present any association in most previous studies 19,27,28." (PMID 32300124, 2020). "Thus, if the association between alcohol drinking and breast cancer risk were real, even though modest, it would be intensified by the genetic modulation of ALDH2 and/or ADH1B, which should make it more detectable." (PMID 19667493, 2009). "No significant impact on breast cancer risk by genotype was seen with individual polymorphisms for either ADH1B or ALDH2 in the analysis controlling for matching factors only or the analysis also controlling for potential confounders." (PMID 19667493, 2009). "We did not observe an association between ADH1B genotype and several risk factors, including first-degree family history of breast cancer, body mass index, parity, breastfeeding or smoking status (data not shown)." (PMID 15886702, 2005). "The analysis revealed no main effect of ADH1B genotype on breast cancer risk (adjusted OR for carriers of ADH1B*2 allele vs ADH1B*1/*1 genotype being 1.0, 95% confidence interval (CI) 0.7–1.4)." (PMID 15886702, 2005). "There was a negative estimate for luminal B breast cancer based on the ADH1B variant only." (PMID 41398582, 2025). "Alcohol consumption increased the risk of breast cancer regardless of ADH1B and ALDH2 genotypes." (PMID 32300124, 2020). "Thus, in the present study, we investigated the association among genetic, functionally established single nucleotide polymorphisms (SNPs) in ADH1B (rs1229984) and ALDH2 (rs671), alcohol consumption, and their combined effects and breast cancer risk in an East-Asian population." (PMID 32300124, 2020). "In the present study, although we did not identify a significant association between ADH1B polymorphism and breast cancer risk, a decreasing trend was observed in those with the C allele, in particular the homozygotes of the C allele, which was consistent with previous studies." (PMID 32300124, 2020). "However, multivariate analysis separately for carriers and noncarriers of the ADH1B*2 allele yielded differences in breast cancer risk associated with increasing levels of alcohol intake." (PMID 15886702, 2005).
breast carcinoma (continued). "Up-regulated expression of COL10A1, MMP11, CST1, GJB2, MMP1, MMP13, and CEACAM6; down-regulated expression of ADH1B, CIDEC, THRSP, GPD1, TIMP4, FABP4, and SCARA5 genes was common in breast cancers of the two populations." (PMID 31292488, 2019). "Several other large studies, however, indicate that SNPs in ADH1B, ADH1C, and CYP2E1 do not modify associations of alcohol intake with breast cancer risk." (PMID 37308906, 2023). "Despite sufficient statistical power, there was no significant impact of ADH1B and ALDH2 on the risk of breast cancer." (PMID 19667493, 2009).
ovarian carcinoma (16 papers, 2014 to 2025). A malignant neoplasm originating from the surface ovarian epithelium. "Among them, ADH1B encodes a protein that is a member of the alcohol dehydrogenase family, and it has been proven to promote mesothelial clearance and ovarian cancer infiltration." (PMID 39680618, 2024). "Additionally, the correlations between ADH1B and tumor-infiltrating immune cells (TIICs) and immune checkpoints in ovarian cancer were deeply studied for an underlying immunotherapy target and ready-made targeted drugs." (PMID 35756990, 2022). "As a drug metabolism-related gene, the high level of ADH1B expression has been reported to be connected to a good prognosis in ovarian cancer, along with its positive correlation with multiple immune cells." (PMID 38462627, 2024). "Analyses of data from public datasets have shown that ADH‐1B (alcohol dehydrogenase 1B) is one of the candidates for forecasting residual ovarian cancer." (PMID 37605299, 2023). "Several other bioinformatic analyses have pointed to the close association of ADH1B with the prognosis of ovarian cancer patients and that ADH1B is a potential source of chemoresistance in ovarian cancer." (PMID 36950684, 2023). "To investigate the relationship between clinical characteristics and ADH1B expression, we divided ovarian cancer patients into two groups with high and low ADH1B expression and performed statistical analysis using the clinical data from the TCGA database." (PMID 35756990, 2022). "Generally, these studies show that ADH1B is a key part of the immune microenvironment and regulates a variety of immune cells against ovarian cancer cells." (PMID 35756990, 2022). "It is a discussible question about the roles of ADH1B on prognosis and immune infiltration in ovarian cancer." (PMID 35756990, 2022). "Differential expression of ADH1B in ovarian cancer can make cells secrete MMP-7 CD-26 and cathepsin to promote cancer progression." (PMID 35433681, 2022). "In summary, the downregulation of ADH1B was illustrated in this study, which was shown with a good prognosis value for ovarian cancer." (PMID 35756990, 2022). "We primarily evaluated the immune infiltration cells related to ADH1B in ovarian cancer through the ssGSEA algorithm with Pearson correlation." (PMID 35756990, 2022). "Overall, the implications of these results were that ADH1B was demonstrated to participate in a variety of immune regulation in ovarian cancer and able to be a new breakthrough in the treatment of ovarian cancer." (PMID 35756990, 2022). "Then, data from TCGA-OV suggested that ADH1B expression is significantly down-regulated in ovarian cancer." (PMID 35756990, 2022). "First, several public databases were used to demonstrate that aberrantly expressed ADH1B influences the progression and prognosis of ovarian cancer." (PMID 35756990, 2022). "The demographic parameters for ovarian cancer patients from the TCGA database based on the ADH1B levels." (PMID 35756990, 2022). "In our study, ADH1B, a drug metabolism-related gene, was down-regulated in ovarian cancer tissues, which indicated a better life span expectancy." (PMID 35756990, 2022). "ADH1B can be considered as a molecular biomarker of residual disease and its overexpression promotes invasion and metastasis in ovarian cancer." (PMID 35756990, 2022). "ADH1B, a drug metabolism-related gene, was reported to play a vital part in the immune regulation of ovarian cancer patients." (PMID 36098688, 2022). "In the current study, we investigated the functional role of ADH1B in promoting ovarian cancer cell invasiveness and contributing to residual disease." (PMID 29861857, 2018). "Having established the role of ADH1B as a molecular predictor of residual ovarian cancer, we sought to determine the functional role of ADH1B in ovarian cancer metastasis." (PMID 29861857, 2018). "We analyzed publicly available datasets of ovarian cancer patients to determine the effect of ADH1B expression on survival." (PMID 29861857, 2018).